DEFB133 (defensin beta 133 (pseudogene))
Description:
Has antibacterial activity.
Gene: Transcribed unprocessed pseudogene on chromosome 6 (49,946,101 to 49,949,444, reverse strand). Ensembl gene ENSG00000214643.
Subcellular location: Secreted
Pathways (Reactome):
Immune System: Beta defensins; Defensins